ATRX (ATRX chromatin remodeler)
Diseases named in the same sentence as ATRX in open-access papers (continued):
Sharing a sentence is not in itself a finding about the gene and the disease.
promyelocytic leukemia (7 papers, 2010 to 2023). "ATRX has been shown to exhibit a physical interaction with the transcriptional regulatory factor death domain associated protein (DAXX) at promyelocytic leukemia nuclear bodies (PML's) in both human and murine somatic cells." (PMID 20885787, 2010). "HDACi treated cells expressed higher levels of some of the host ND10 proteins (promyelocytic leukemia and ATRX), which may explain the lower number of viral genomes initiating expression per cell." (PMID 27999572, 2016). "Interestingly, this ATRX/DAXX/H3.3 complex is strongly associated with nuclear compartments known as promyelocytic nuclear bodies (PML-NBs), which is a frequently mutated oncogenic driver in acute promyelocytic leukemias." (PMID 38066546, 2023). "There is also evidence for ATF7IP2 and ATRX transcriptional activation role, through SP1 and DAXX interaction, in promyelocytic leukemia nuclear bodies." (PMID 28293299, 2017). "Notably, the EBV tegument protein BNRF1 targets ATRX and DAXX for sequestration in promyelocytic leukemia (PML) bodies at this time point, suggesting that HIRA and newly induced CAF1 may be responsible." (PMID 33109754, 2020).
Alpha-thalassemia - X-linked intellectual disability syndrome (6 papers, 2021 to 2024). "We studied the function and potential pathogenic mechanism of the mutant gene and found that the novel mutation resulted in haploinsufficiency of the ATRX gene, which caused ATR-X syndrome." (PMID 35127601, 2021). "ATR-X syndrome is caused by mutations in the ATRX gene, which is located on Xq21.1, containing 37 exons and spanning approximately 280 kb." (PMID 35127601, 2021). "Using exome analysis for a male CS patient, we identified ERCC6 variants as well as an ATRX variant at the splice acceptor site of intron 1, even though this patient was not considered to have ATR-X syndrome." (PMID 36104326, 2022).
angiosarcoma (6 papers, 2019 to 2025). A malignant tumor arising from the endothelial cells of the blood vessels. "Prior studies of angiosarcoma noted high rates of ATRX mutation, high TMB, and PDL-1 positivity, particularly among head and neck angiosarcoma, while we observed a DDR alteration rate of 25% and ATRX alteration rate of 13% among angiosarcoma." (PMID 40563612, 2025). "The findings by Liau and colleagues suggest that the ALT phenotype and ATRX loss are highly correlated with angiosarcomas, especially the primary hepatic angiosarcomas." (PMID 34069193, 2021). "In a cohort of 118 angiosarcoma cases, Panse and colleagues found 6% (7/118) to have ATRX loss, and like the findings of Liau and colleagues, they were all primary angiosarcoma." (PMID 34069193, 2021). "Recent studies showed that angiosarcomas are highly correlated with the ALT phenotype and ATRX loss, with ALT being prevalent in 11–24% of angiosarcomas and ATRX loss in 6–18% of angiosarcomas." (PMID 34069193, 2021). "Similarly, all ATRX-deficient angiosarcomas were primary angiosarcomas, with hepatic angiosarcomas having the highest rate of ATRX loss relative to non-hepatic tumors." (PMID 34069193, 2021). "In addition, they found that angiosarcoma patients with ATRX-mutant had decreased event-free survival compared to patients that retained ATRX expression." (PMID 34069193, 2021). "We also found KDR-ATRX to be mutually exclusive, which may indicate distinct biologies in angiosarcoma subclasses: angiogenesis dysfunction (KDR) and chromatin/telomere dysfunction (ATRX)." (PMID 41301029, 2025).
autism (6 papers, 2020 to 2026). Persistent deficits in social interaction and communication and interaction as well as a markedly restricted repertoire of activity and interest as well as repetitive patterns of behavior. "Previously, our lab identified several ATRX target genes related to synaptic function, including Neuroligin 4 (Nlgn4) that functions at the post-synaptic cleft and is a known autism-associated gene." (PMID 37957569, 2023). "We previously showed that mice with conditional ATRX ablation in forebrain excitatory neurons display deficits in fear memory and autism-related behaviors, with some effects exhibiting sexual dimorphism." (PMID 41724591, 2026). "MEAs have been deployed to investigate gene mutations associated with monogenic forms of autism in hiPSC-neurons such as CNTN5, EHMT2, KCNQ2, ATRX, and SCN2A." (PMID 37441676, 2023). "It has been reported that the ATRX gene had a positive effect on transcription as the Ngln4X gene, a known autism-related gene." (PMID 35444965, 2022). "As a third study with overexpression of L1s, we analyzed a dataset derived from knocking out the ATRX gene in cultured neurons and iPSC cell lines as a model of autism." (PMID 36552034, 2022). "The mechanisms by which ATRX mutations lead to autism and autistic-like behaviours are not yet known." (PMID 32580781, 2020).
epilepsy (6 papers, 2013 to 2026). A brain disorder characterized by episodes of abnormally increased neuronal discharge resulting in transient episodes of sensory or motor neurological dysfunction, or psychic dysfunction. "ATRX loss was associated with seizure freedom at the most recent follow up, suggesting that tumor molecular features may help prognosticate epilepsy outcomes." (PMID 42319547, 2026). "ATRX mutations may indirectly affect the survival and differentiation of inhibitory interneurons, potentially leading to an imbalance between excitatory and inhibitory activity and a predisposition to epilepsy." (PMID 40103938, 2025).
gastric cancer (6 papers, 2021 to 2024). A primary or metastatic malignant neoplasm involving the stomach. "A recent study indicated that female gastric cancer patients with ATRX mutations were more likely to benefit from ICI treatment." (PMID 39555056, 2024). "Thirdly, one study found that the ATRX gene was found to mutate more frequently in female gastric cancer patients." (PMID 36385957, 2022). "In the patients of gastric cancer, ATRX mutation patients trended toward a longer overall survival (median, not reached vs 13 months, log rank P = 0.194)." (PMID 33678158, 2021). "We have selected the non-gastric cancer cohorts with ATRX mutation frequency more than 10%, including LGG (39.2%), UCEC (24.3%), SARC (16.9%), GBM (10.4%), CESC (10.4%), COAD (10.3%)." (PMID 33678158, 2021). "Overall, these results indicate the ATRX mutation in gastric cancer patients might exist sex biases." (PMID 33678158, 2021). "Notably,ATRX mutations are frequently observed in female gastric cancer patients with high microsatellite instability (MSI), tumor mutational burden (TMB), and programmed death-ligand 1 (PD-L1) expression; these characteristics are purported to be predictive biomarkers for immunotherapy response." (PMID 37954063, 2023).
glioneuronal tumor (6 papers, 2020 to 2026). "Glioneuronal tumor with ATRX alteration, kinase fusion, and anaplastic features (GTAKA) is a rare pathological subtype of the central nervous system, with currently limited research available." (PMID 41659726, 2026). "Among these, Glioneuronal Tumor with ATRX Alteration, Kinase Fusion, and Anaplastic Features (GTAKA) has recently been delineated as a distinct molecular entity." (PMID 41397922, 2025). "In conclusion of histology and molecular analyses, an integrated diagnosis of “Glioneuronal tumor with ATRX alteration, kinase fusion and anaplastic features (GTAKA)” was established." (PMID 41397922, 2025). "The methylation data showed a match with the methylation class super-family Adult Type Diffuse Gliomas with the highest score for the methylation class “Glioneuronal tumor with ATRX alteration, kinase fusion and anaplastic features (novel)”." (PMID 41397922, 2025). "In summary, our findings highlight a novel type of glioneuronal tumor driven by different RTK fusions accompanied by recurrent alterations in ATRX and homozygous deletions of CDKN2A/B." (PMID 36933012, 2023). "Given their molecular characteristics in addition to anaplastic features, we suggest the term glioneuronal tumor with ATRX alteration, kinase fusion and anaplastic features (GTAKA) to describe these tumors." (PMID 36933012, 2023).
liposarcoma (6 papers, 2018 to 2025). A usually painless malignant tumor that arises from adipose tissue. "For example, loss of ATRX and subsequent activation of ALT has been observed in liposarcomas and correlates with poor overall survival." (PMID 29796169, 2018).
microcephaly (6 papers, 2016 to 2026). A congenital or acquired developmental disorder in which the circumference of the head is smaller than normal for the person's age and sex. "In addition, researchers found the identified defects in the ATRX-null developing brain were intimately linked to microcephaly phenotype in epigenetic etiology studies of ATR-X syndrome and ATRX protein played an important role in learning and memory." (PMID 35444965, 2022).
neuroendocrine carcinoma (6 papers, 2017 to 2025). A malignant neuroendocrine neoplasm composed of cells containing secretory granules that stain positive for NSE and chromogranin.
developmental delay (5 papers, 2014 to 2024). "Duplication of Xq13.2-Xq21.31, the region containing YWHAZP8, along with other genes such as ATRX and PCDH11X, has been reported in a clinical case associated with X-inactivation, resulting in developmental delays and seizures in a boy with pubertal gynecomastia." (PMID 38674334, 2024). "In three patients with myoclonus as primary phenotype, mutation of TUBB2B (OMIM 610031), ATRX, or DHDDS (developmental delay and seizures with or without movement abnormalities; OMIM 617836) gene were found to be causative." (PMID 35719373, 2022).
hepatocellular carcinoma (5 papers, 2020 to 2023). A malignant tumor that arises from hepatocytes. "The tumor suppressor gene ATRX is frequently mutated in a variety of tumors, including hepatocellular carcinoma (HCC) and glioma, and has a minimal response to current therapies." (PMID 34598686, 2021).
low grade glioma (5 papers, 2022 to 2025). A grade I or grade II glioma arising from the central nervous system. "In contrast, ATRX mutation (43.81%), which was considered as a molecular signature of low-grade glioma (LGG), was more likely to occur in the low SASP Score group than high SASP Score group (14.76%)." (PMID 40781221, 2025).
lymph node metastasis (5 papers, 2017 to 2024). "Loss of ATRX or TSC2 has been significantly associated with lymph node metastasis, and combined loss of TSC2 and ATRX has been determined as an independent prognostic factor for shorter RFS in G2 pNENs." (PMID 36556070, 2022).
medulloblastoma (5 papers, 2013 to 2024). A malignant, invasive embryonal neoplasm arising from the cerebellum. "Intriguingly, when surveying 43 pediatric metastatic medulloblastoma, Minasi and colleagues recently found that 30% of tumors showed negative ATRX nuclear staining, suggesting that ALT positivity in medulloblastoma may be higher than previously reported." (PMID 34069193, 2021).
oligodendroglial tumor (5 papers, 2014 to 2024). Oligodendrogliomas are cerebral tumors that are differentiated from other gliomas on the basis of their unique genetic characteristics and better response to chemotherapy. "Similarly, ATRX mutations were also enriched in astrocytic and mixed lineage tumors but only 2/65 oligodendroglial tumors contained ATRX mutations." (PMID 25257301, 2014). "Consistent with high frequencies of wildtype ATRX in oligodendroglial tumors, ATRX protein expression was high in these tumors while astrocytic and mixed lineage tumors in which ATRX is frequently mutated (loss of function events) exhibited low protein levels." (PMID 25257301, 2014). "Conversely oligodendroglial tumors demonstrated significantly increased ATRX protein expression compared to astrocytic and mixed lineage tumors, however ATRX mutations were not correlated with ATRX expression, consistent with previously published studies." (PMID 25257301, 2014).
pancreatic neuroendocrine cancers (5 papers, 2012 to 2023).
brain cancer (4 papers, 2020 to 2022). A primary or metastatic malignant neoplasm affecting the brain. "The mechanism is similar in the frequent mutations in H3.3 and ATRX in pediatric brain cancer, which compromise chromatin structure and promotes genomic instability and ALT." (PMID 32117990, 2020). "These strategies can now be validated and optimised in prospective clinical studies, and can be extended to identify other important molecular alterations, such as ATRX loss, 1p/19q co-deletion and/or MGMT hypermethylation, with which brain cancer type can be stratified pre-operatively." (PMID 33302429, 2020).
colon carcinoma (4 papers, 2015 to 2024). "We also showed that successful knockout of ATRX using CRISPR/Cas9 technology or rAAV in epithelial-derived HCT116 colon carcinoma cells did not affect telomerase expression nor activate ALT." (PMID 26001292, 2015).
cutaneous melanoma (4 papers, 2021 to 2023). A primary melanoma arising from atypical melanocytes in the skin. "Nevertheless, ATRX may also play an important role in cutaneous melanomas, as a 2020 study demonstrated that high ATRX expression is associated with increased survival rates." (PMID 37373134, 2023). "By comparison with cutaneous melanoma, mucosal melanoma has a decreased frequency of BRAF mutations (<10%) and an increased frequency of mutations of CD117 or c-KIT (40%), along with other somatic mutation (SF3B1, ATRX, ARID2, and SETD2)." (PMID 35334544, 2022). "ATRX is part of SWI/SNF family of chromatin remodelers, its mutations occurring in different tumours of neural crest cell origin, such as neuroblastoma, low-grade glioma, and glioblastoma, as well as in cutaneous melanoma." (PMID 35334544, 2022).
intellectual disability syndrome (4 papers, 2020 to 2023). "Mutations of ATRX result in the ATR-X intellectual disability syndrome and have been identified in autism spectrum disorder (ASD) patients." (PMID 32580781, 2020).
leukemia (4 papers, 2010 to 2025). A malignant (clonal) hematologic disorder, involving hematopoietic stem cells and characterized by the presence of primitive or atypical myeloid or lymphoid cells in the bone marrow and the blood. "ATRX, like DAXX, can further associate with promyelocytic leukaemia nuclear bodies (PML-NBs) and has been proposed to contribute to DAXX/H3.3/ATRX associates with pericentric heterochromatin regions that are transcriptionally silenced by H3K9 trimethylation (H3K9me3)." (PMID 34680268, 2021).
lung carcinoma (4 papers, 2019 to 2025).
undifferentiated pleomorphic sarcoma (4 papers, 2021 to 2024). An undifferentiated soft tissue sarcoma characterized by the presence of a pleomorphic malignant cellular infiltrate. "Consistent with these genetic studies, loss of ATRX expression occurs in 20–30% of undifferentiated pleomorphic sarcoma (UPS) and leiomyosarcomas." (PMID 38477352, 2024).
acute myeloid leukemia (3 papers, 2013 to 2020). Acute myeloid leukemia (AML) is a group of neoplasms arising from precursor cells committed to the myeloid cell-line differentiation. "Most DAXX and ATRX mutations are mutually exclusive and result in loss of expression, apart from a missense mutation found in acute myeloid leukemia (AML)." (PMID 23760585, 2013).
alpha-thalassemia mental retardation syndrome (3 papers, 2019 to 2021). "Additionally, mutations in ATRX genes are associated with an X-linked syndrome, alpha-thalassemia mental retardation syndrome (ATRX)." (PMID 34068021, 2021). "These may include MGMT promoter methylation, isocitrate dehydrogenase (IDH) mutations, telomerase reverse transcriptase (TERT) mutations, 1p/19q co-deletion and alpha-thalassemia mental retardation syndrome (ATRX) mutations." (PMID 34794398, 2021). "For example, Rad54-like subfamily was further classified into four subgroups, namely, Rad54, J-binding protein 2 (JBP2), alpha thalassemia/mental retardation syndrome X-linked (ATRX), and DRD1, containing 2 (SlCHR22 and SlCHR32), 1 (SlCHR25), 1 (SlCHR20), and 10 SlCHRs, respectively." (PMID 31049349, 2019).